HCST (hematopoietic cell signal transducer)
Description:
Transmembrane adapter protein which associates with KLRK1 to form an activation receptor KLRK1-HCST in lymphoid and myeloid cells; this receptor plays a major role in triggering cytotoxicity against target cells expressing cell surface ligands such as MHC class I chain-related MICA and MICB, and UL16-binding proteins (ULBPs); these ligands are up-regulated by stress conditions and pathological state such as viral infection and tumor transformation. Functions as a docking site for PI3-kinase PIK3R1 and GRB2. Interaction of ULBPs with KLRK1-HCST triggers calcium mobilization and activation of the PIK3R1, MAP2K/ERK, and JAK2/STAT5 signaling pathways. Both PIK3R1 and GRB2 are required for full KLRK1-HCST-mediated activation and ultimate killing of target cells. In NK cells, KLRK1-HCST signaling directly induces cytotoxicity and enhances cytokine production initiated via DAP12/TYROBP-associated receptors. In T-cells, it provides primarily costimulation for TCR-induced signals. KLRK1-HCST receptor plays a role in immune surveillance against tumors and is required for cytolysis of tumors cells; indeed, melanoma cells that do not express KLRK1 ligands escape from immune surveillance mediated by NK cells.
Synonyms: DAP10; KAP10; PIK3AP; DKFZP586C1522
Tractability: Antibody: its Gene Ontology location is reachable by antibodies, with high confidence; UniProt predicts a signal peptide or a membrane-spanning region.
Gene: Protein-coding gene on chromosome 19 (35,900,635 to 35,904,377, forward strand). Ensembl gene ENSG00000126264.
Subcellular location: Membrane
Subcellular location (Human Protein Atlas): Golgi apparatus; Plasma membrane; Vesicles
Pathways (Reactome):
Immune System: Immunoregulatory interactions between a Lymphoid and a non-Lymphoid cell
Gene Ontology:
Molecular function: phosphatidylinositol 3-kinase binding; protein binding; protein-macromolecule adaptor activity; signaling receptor binding
Biological process: natural killer cell mediated cytotoxicity; positive regulation of phosphatidylinositol 3-kinase/protein kinase B signal transduction; protein phosphorylation; regulation of immune response
Cellular component: cell surface; plasma membrane; membrane
Genetic constraint (gnomAD): Loss-of-function variants: 12 observed, 11.44 expected, observed/expected ratio (o/e) 1.05, 90% interval 0.67 to 1.66. The upper end of that interval is the gene's LOEUF score, 1.66, which puts it in group 6 of 6, group 1 being the genes least tolerant of losing a copy. Missense variants: 102 observed, 125.36 expected, observed/expected ratio (o/e) 0.81, 90% interval 0.69 to 0.96. Synonymous variants: 59 observed, 56.22 expected, observed/expected ratio (o/e) 1.05, 90% interval 0.85 to 1.3.
Homologues: Orthologues: chimpanzee HCST (98% identical), macaque HCST (84% identical), rabbit HCST (75% identical), mouse Hcst (67% identical), rat Hcst (66% identical), dog HCST (63% identical).
Diseases named in the same sentence as HCST in open-access papers:
HCST is named in the same sentence as 34 diseases in open-access papers, as found by Europe PMC text mining. Sharing a sentence is not in itself a finding about the gene and the disease. The quoted sentences say what the papers report.
breast carcinoma (4 papers, 2014 to 2025). "Vav3 and HCST play a role in the development of human breast cancer." (PMID 40005880, 2025).
viral infections (2 papers, 2023). "Owing to the critical role of HCST and STAT2 in the inflammatory response, we further explored the potential mechanism regulated by these two hub genes after virus infection in myocardial cells." (PMID 38025532, 2023).
aneurysm (1 paper, 2015). Bulging or ballooning in an area of an artery secondary to arterial wall weakening. "A role for HCST (DAP10) in aneurysm or atherosclerosis has not been described previously, but the NKD2D/DAP10 receptor complex is known to play a crucial role in macrophage activation further supporting the results of macrophage activation seen in the AAA tissue." (PMID 25993291, 2015).
COVID-19 (1 paper, 2023). A disease caused by infection with severe acute respiratory syndrome coronavirus 2. "Previous studies have identified the HCST as a key immune-related gene involved in m6A regulator-mediated RNA methylation modification patterns in AF, suggesting its potential value as an intervention target in the AF immune microenvironment under the COVID-19 burden." (PMID 38025532, 2023).
lymph node metastasis (1 paper, 2021). "In addition, high HCST expression has been associated with grade (p = 0.005), TNM stage (p = 0.001), lymph node metastasis (p = 0.004), and invasion depth (p = 0.018) in ccRCC." (PMID 33968730, 2021). "Analysis using TCGA clinical data and R version 4.0.2 showed that HCST expression was correlated with grade (p = 0.005), TNM stage (p = 0.001), lymph node metastasis (p = 0.004), and invasion depth (p = 0.018), but not age (p = 0.721), sex (p = 0.292), or distant metastasis (p = 0.218)." (PMID 33968730, 2021).
renal carcinoma (1 paper, 2021). A carcinoma arising from the epithelium of the renal parenchyma or the renal pelvis. "We performed a primary test using qRT-PCR to determine the expression of the HCST in renal cancer tissues and compared them with para-cancer tissues." (PMID 33968730, 2021).
renal cell carcinoma (1 paper, 2023). "High HCST expression leads to significant enrichment in cell adhesion, tumor formation, and immune and inflammatory responses in a renal cell carcinoma specimen." (PMID 36993823, 2023).
tumor (36 papers, 2014 to 2025). "The GSEA study further indicated that the pathways enriched in tissue samples with high HCST expression were mainly related to cell adhesion, tumor formation, and the immune response." (PMID 33968730, 2021). "High HCST expression was also closely correlated with the levels of tumor-infiltrating immune cells, especially DCs." (PMID 33968730, 2021). "Further analysis with the use of the TIMER database revealed that the HCST gene was prominently correlated with the tumor infiltration of B cells, CD8+ T cells, and neutrophils and strongly interrelated with DCs." (PMID 33968730, 2021). "Tumor-infiltrating clusters NK1 and NK5 showed high expression of NK-activating receptors, including NKG2D-DAP10 (KLRK1/HCST), NKG2C (KLRC2), CD94 (KLRD1), and NKp30 (NCR3), suggesting that they were robustly activated." (PMID 40315330, 2025). "CD74, GIMAP4, HCST, and HLA-DMA not only showed good clinical phenotype correlation but also correlated with M2 type macrophages, tumor purity, and immune score." (PMID 33854546, 2021). "In TCGA/GEO databases, the high HCST expression in tumor tissues was significantly correlated to the TMN stage, tumor grade, invasion depth, and lymphatic metastasis (p < 0.05)." (PMID 33968730, 2021). "In addition, high levels of HCST, C3AR1, GBP4, LY96, ANKRD22, FPR3 and FCGR2A, have also been related to immune activation and/or inflammatory response in tumours; however, their role in basal-like breast malignancies are yet to be uncovered." (PMID 28351365, 2017).
cancer (8 papers, 2011 to 2023). A tumor composed of atypical neoplastic, often pleomorphic cells that invade other tissues. "Consistently, the HCST was observed upregulated with the R version 4.0.2 software analysis of TCGA data, of which HCST mRNA levels of cancer and para-cancerous tissue are from the same ccRCC patients." (PMID 33968730, 2021).
HCST also shares sentences with these, for which no sentence is quoted: osteosarcoma (3 papers); B cell lymphoma (2); ovarian carcinoma (2); pancreatic cancer (2); Alzheimer disease (1); atherosclerosis (1); Autoimmunity (1); B-cell acute lymphoblastic leukemia (1); bacterial infection (1); bladder cancer (1); clear cell renal cell carcinoma (1); Ewing sarcoma (1); gastric cancer (1); hematological malignancies (1); hepatocellular carcinoma (1); infection (1); invasive breast carcinoma (1); lung adenocarcinoma (1); lung carcinoma (1); malignant pleural mesothelioma (1); melanoma (1); neuroblastoma (1); non-small cell lung carcinoma (1); Sepsis (1); Splenomegaly (1).